PTPMT1 (protein tyrosine phosphatase mitochondrial 1)
Description:
Lipid phosphatase which dephosphorylates phosphatidylglycerophosphate (PGP) to phosphatidylglycerol (PG) (By similarity). PGP is an essential intermediate in the biosynthetic pathway of cardiolipin, a mitochondrial-specific phospholipid regulating the membrane integrity and activities of the organelle. Has also been shown to display phosphatase activity toward phosphoprotein substrates, specifically mediates dephosphorylation of mitochondrial proteins, thereby playing an essential role in ATP production (By similarity). Has probably a preference for proteins phosphorylated on Ser and/or Thr residues compared to proteins phosphorylated on Tyr residues (By similarity). Probably involved in regulation of insulin secretion in pancreatic beta cells (By similarity). Prevents intrinsic apoptosis, by regulating mitochondrial membrane integrity.
Synonyms: MOSP; PLIP; PNAS-129; DUSP23; NEDAXBA
Tractability: Antibody: UniProt places it where antibodies can reach, with medium confidence. PROTAC: ubiquitination databases record sites on it; its protein half-life has been measured; a small molecule that binds it is known.
Target class: Enzyme; Phosphatase
Gene: Protein-coding gene on chromosome 11 (47,565,430 to 47,573,461, forward strand). Ensembl gene ENSG00000110536.
Subcellular location: Mitochondrion inner membrane
Subcellular location (Human Protein Atlas): Mitochondria
Pathways (Reactome):
Metabolism: Synthesis of PG
Gene Ontology:
Molecular function: protein binding; phosphatidylglycerophosphatase activity; phosphatidylinositol-5-phosphate phosphatase activity; protein serine/threonine phosphatase activity; phosphoprotein phosphatase activity; protein tyrosine phosphatase activity
Biological process: cardiolipin biosynthetic process; mitochondrial fragmentation involved in apoptotic process; regulation of intrinsic apoptotic signaling pathway; phosphatidylglycerol biosynthetic process
Cellular component: mitochondrion; nucleus; mitochondrial inner membrane
Genetic constraint (gnomAD): Loss-of-function variants: 11 observed, 17.65 expected, observed/expected ratio (o/e) 0.62, 90% interval 0.39 to 1.03. The synonymous counts are far from expectation, so gnomAD's model fits this gene poorly and the ratio says little. Missense variants: 262 observed, 244.68 expected, observed/expected ratio (o/e) 1.07, 90% interval 0.97 to 1.19. Synonymous variants: 132 observed, 101.01 expected, observed/expected ratio (o/e) 1.31, 90% interval 1.13 to 1.51.
Homologues: Orthologues: chimpanzee PTPMT1 (99% identical), macaque PTPMT1 (97% identical), dog PTPMT1 (88% identical), pig PTPMT1 (85% identical), mouse Ptpmt1 (81% identical), rat Ptpmt1 (81% identical), guinea pig PTPMT1 (65% identical), rabbit PTPMT1 (56% identical), tropical clawed frog ptpmt1 (51% identical), zebrafish ptpmt1 (50% identical), Drosophila melanogaster PTPMT1 (39% identical), Caenorhabditis elegans F28C6.8 (32% identical). Paralogues in human: DUSP16 (25% identical), DUSP8 (24% identical), SSH2 (23% identical), SSH3 (23% identical), SSH1 (23% identical), DUSP1 (22% identical), DUSP14 (22% identical), DUSP2 (22% identical), DUSP26 (21% identical), DUSP4 (21% identical), DUSP5 (21% identical), DUSP6 (21% identical), and 19 more.
Diseases named in the same sentence as PTPMT1 in open-access papers:
PTPMT1 is named in the same sentence as 28 diseases in open-access papers, as found by Europe PMC text mining. Sharing a sentence is not in itself a finding about the gene and the disease. The quoted sentences say what the papers report.
breast carcinoma (5 papers, 2021 to 2025). "SRSF1 promoted the proliferation and migration of breast cancer cells and inhibited the apoptosis of breast cancer cells via regulating the alternative splicing of PTPMT1." (PMID 40176901, 2025). "It accelerates breast cancer progression by regulating exon 3 splicing of PTPMT1 (a phosphatase), altering the function of PTPMT1 and then activating the AKT/C-MYC signaling pathway, which promotes breast cancer cell proliferation and migration, and inhibits apoptosis." (PMID 40129567, 2025). "SRSF1 exerts oncogenic roles in breast cancer partially by regulating the alternative splicing of PTPMT1, which could be a therapeutic target candidate in breast cancer and a prognostic factor in HR + breast cancer patients." (PMID 36065311, 2022).
glaucoma (4 papers, 2022 to 2025). Increased pressure in the eyeball due to obstruction of the outflow of aqueous humor. "For glaucoma, PTPMT1 is associated with optic nerve atrophy and elevated intraocular pressure, which are features of glaucoma and increase the risk of glaucoma." (PMID 39408566, 2024).
hepatocellular carcinoma (3 papers, 2021 to 2025). A malignant tumor that arises from hepatocytes. "In this study, we mainly investigated the role of PTPMT1 in hepatocellular carcinoma (HCC) ferroptosis, a new type of cell death accompanied by significant iron accumulation and lipid peroxidation." (PMID 40189563, 2025). "In PTPMT1 knockout hepatocellular carcinoma cells, mitochondria had altered morphology and generated less energy exhibiting slower growth, lower viability, and less aggressive phenotypes." (PMID 35805888, 2022).
lung carcinoma (3 papers, 2020 to 2021). "During radioactive tracer treatment of lung cancer cells, SRSF1 knockdown could sensitize cancer cells to irradiation via regulation of PTPMT1 splicing." (PMID 33996533, 2021).
AIDS-related lymphoma (1 paper, 2024). "We further tested the effects of PTPMT1 KO in BLs, a major EBV-associated, AIDS-related lymphoma." (PMID 38659762, 2024).
dilated cardiomyopathy (1 paper, 2023). Cardiomyopathy which is characterized by dilation and contractile dysfunction of the left and right ventricles. "Deletion of Ptpmt1 from the heart ultimately leads to dilated cardiomyopathy and heart failure." (PMID 37672386, 2023).
epilepsy (1 paper, 2025). A brain disorder characterized by episodes of abnormally increased neuronal discharge resulting in transient episodes of sensory or motor neurological dysfunction, or psychic dysfunction. "Notably, we found eight proteins shared by stroke and epilepsy (e.g., SH3BGRL3, PTPMT1), nine shared by epilepsy and VaD (e.g., DOCK7, BCAN), and ten by stroke and VaD (e.g., MTHFR, UVRAG), suggesting common pathogenic axes like inflammation and cellular stress." (PMID 40624693, 2025). "There were 8 proteins shared between epilepsy and ischemic stroke: SH3BGRL3, BPNT1, PTPMT1, PACSIN3, MIPEP, CMC2, ABCA5, and PTK2B." (PMID 40624693, 2025).
heart failure (1 paper, 2023). Inability of the heart to pump blood at an adequate rate to meet tissue metabolic requirements. "Prolonged mitochondrial energy sources switch from carbohydrates to lipids such as that caused by Ptpmt1 depletion is detrimental to the skeletal muscle and heart but not the liver and adipose, ultimately leading to muscle atrophy and heart failure." (PMID 37672386, 2023).
insomnia (1 paper, 2022). A sleep disorder characterized by difficulty in falling asleep and/or remaining asleep. "For example, the PTPMT1 gene, located at 11p11.2, was co-independently TWAS-significant for AD, insomnia, and sleep duration and was simultaneously a prominent shared locus among AD and sleep duration." (PMID 35656316, 2022). "Consequently, we highlighted the potentially interesting functions of the novel associations for PRL (6p22.3) between AD and snoring, as well as the focused PTPMT1(11p11.2) and KAT8(16p11.2) regions shared between AD and insomnia or sleep duration." (PMID 35656316, 2022).
insulinoma (1 paper, 2013). "Additionally, PTPMT1 knockdown has previously been characterized in an insulinoma cell line, in which transient knockdown of this gene was sufficient to induce significant increases in cellular ATP levels relative to a non-targeting siRNA control." (PMID 23326511, 2013).
liver cancer (1 paper, 2016). An epithelial or non-epithelial malignant neoplasm that arises from the liver. "We identified that the change in the miRNA expression profile of MIR335 (p-value < 0.808) results in the significant change in the gene expression profile of PTPMT1 (p-value < 8.4☓10-4) between normal liver cells and liver cancer cells." (PMID 26897165, 2016).
mitochondrial myopathies (1 paper, 2023). "Gömöri trichrome staining revealed ragged red fibers in Ptpmt1 knockout skeletal muscles, as observed in various types of human mitochondrial myopathies." (PMID 37672386, 2023).
pancreatic cancer (1 paper, 2024). "In our previous study, we identified NDUFS2 as a downstream factor of PTPMT1 in pancreatic cancer, but the precise role has not yet been validated." (PMID 38653740, 2024).
renal carcinoma (1 paper, 2013). A carcinoma arising from the epithelium of the renal parenchyma or the renal pelvis. "We found that 786-0 cells, a renal carcinoma cell lines, were not significantly affected by PTPMT1 knockdown with either siRNA (data not shown)." (PMID 23326511, 2013).
renal cell carcinoma (1 paper, 2025). "Renal cell carcinomas (RCC) have recently been shown to exhibit a high abundance of phosphatidylglycerols, which are products of the protein-tyrosine phosphatase mitochondrial 1 enzyme (PTPMT1) and precursors of cardiolipins." (PMID 40897466, 2025).
cancer (11 papers, 2013 to 2025). A tumor composed of atypical neoplastic, often pleomorphic cells that invade other tissues. "To determine if the loss of PTPMT1 induces cell death in only a subpanel of cell lines (such as HeLas), or has similar effects in other transformed cells, we chose a panel of cancer cell lines that are highly amenable to siRNA transfection (all >95% transfectable, data not shown)." (PMID 23326511, 2013). "Our data suggest that inhibition of PTPMT1 causes a metabolic crisis in cancer cells that induces cell death, and may be a mechanism by which cancer cells can be sensitized to currently available therapies." (PMID 23326511, 2013). "SRSF1 proteins belong to an important splicing factor (SF) family and bind to different splicing regulatory elements (SREs) to promote or inhibit splicing, such as oncogenic splice-switching of PTpMT1, which promoting the progression of cancer." (PMID 40176901, 2025). "Previous studies found that PTPMT1 inhibited apoptosis and promoted proliferation in cancer cells, indicating the oncogenic role of PTPMT1." (PMID 33992102, 2021). "PTPMT1 is localized in mitochondria and its downregulation is sufficient to promote cancer cell death." (PMID 30369943, 2018). "Recently, it has been proposed that down-regulation of PTPMT1 is sufficient to trigger cancer cell death, and TRIM27 participates in regulating cell proliferation in the development of cancer." (PMID 26897165, 2016). "Conversely, we have classified PTPMT1 as a ‘survival phosphatase’ as its knockdown induces cell death in a large number of cancer cell lines." (PMID 24709986, 2014). "Overall, our study demonstrates that downregulation of PTPMT1 is sufficient to induce apoptosis at high doses, or sensitizes cancer cells to chemotherapeutic treatment at low doses." (PMID 23326511, 2013). "Before its identification as a specific inhibitor of PTPMT1 phosphatase activity, alexidine dihydrochloride had been shown to induce apoptosis in cancer cells." (PMID 23326511, 2013). "Here we report that downregulation of PTPMT1 activity is sufficient to induce apoptosis of cancer cells." (PMID 23326511, 2013). "Here, we demonstrate that RNAi-mediated silencing of PTPMT1 is sufficient to induce cancer cell death." (PMID 23326511, 2013). "Thus, our study provides a new therapeutic strategy toward cancer treatment that activating PTPMT1 to dephosphorylate 4EBP1 which leads to apoptosis from the core region of the tumor." (PMID 36575176, 2022). "Collectively, our results demonstrate that SRSF1 might promote cancer cell growth partially through the SRSF1/PTPMT1 splice switching AKT/C-MYC signaling axis." (PMID 33992102, 2021). "We have confirmed a physical interaction between MK-STYX and PTPMT1 in cancer cells." (PMID 24709986, 2014). "Subsequently, we hypothesize that this temporary metabolic shift cannot be sustained long-term in cancer cells, and, 72–96 hours after silencing of PTPMT1, leads to cancer cell death by apoptosis." (PMID 23326511, 2013). "Importantly, deficiencies in cellular cardiolipin levels have been linked to apoptosis, leading us to investigate if PTPMT1 knockdown in cancer cells alters this mitochondrial lipid." (PMID 23326511, 2013). "Additionally, we explored the effects of the PTPMT1-targeting compound, alexidine dihydrochloride, in its ability to both induce cell death in cancer cells as well as to sensitize these cells to chemotherapeutics at sublethal doses." (PMID 23326511, 2013). "Interestingly, alexidine dihydrochloride treatment shares many intriguing phenotypes with PTPMT1 knockdown: the compound has previously been noted for its ability to induce mitochondrial dysfunction and subsequent apoptosis in a variety of cancer cell lines." (PMID 23326511, 2013). "Additionally, sublethal downregulation of PTPMT1 synergizes with low doses of paclitaxel to promote cancer cell death." (PMID 23326511, 2013).
cancer (continued). "Additionally, the silencing of PTPMT1 decreases cardiolipin levels in cancer cells, while selectively increasing ATP levels in glycolytic media." (PMID 23326511, 2013). "Because PTPMT1 is a key regulator of phospholipid biosynthesis, in particular cardiolipin, these data suggest that dysregulated mitochondrial lipid metabolism could be a novel mechanism by which cancer cells can resist therapeutic treatments." (PMID 24709986, 2014). "The proposed role of cardiolipin in the normal apoptotic process, coupled with the robust cell-death inducing phenotype of alexidine dihydrochloride, led us to hypothesize that downregulation of PTPMT1 gene expression would induce an apoptotic cellular fate in cancer cells." (PMID 23326511, 2013). "Given the apoptotic induction seen in cancer cells when PTPMT1 is knocked down, it is possible that this gene has additional functions which are critical for cancer cell viability yet independent of cardiolipin synthesis." (PMID 23326511, 2013). "The downregulation of PTPMT1 in pancreatic beta cells has been shown to increase cellular ATP levels and insulin production, however, the generalized role of PTPMT1 in cancer cells has not been characterized." (PMID 23326511, 2013).
tumor (8 papers, 2013 to 2025). "Treatment with a PTPMT1 inhibitor (AD) revealed that the tumors acquire more a more aggressive phenotype upon histology and that AD blocked lung metastasis in the orthotopic tumor model." (PMID 34912798, 2021). "Deletion or inhibition of protein tyrosine phosphatase, mitochondrial 1 (PTPMT1) disrupts mitochondrial metabolic flexibility in CD8+ T cells, leading to reduced effector development, accelerated exhaustion, and increased tumor growth." (PMID 40546111, 2025). "Consistent with our data, the ratio of PTPMT1 E3 and SMARCD1 E5 exclusion was decreased in tumor samples compared to paired normal samples, while TERF1 E7 exhibited the opposite AS trend." (PMID 33992102, 2021). "Consistent with a previous analysis, a trend of an increased ratio of PTPMT1 E3 and SMARCD1 exon 5 (E5) inclusion isoforms was observed in tumor tissues compared to normal tissues (n = 6)." (PMID 33992102, 2021). "Importantly, current data implies that inhibition of PTPMT1 in normal, non-transformed cells does not cause cell death and thus, within a critical therapeutic window, could be a specific treatment for tumor cells while minimizing off-target effects to normal cells." (PMID 23326511, 2013). "Collectively, these data suggest that while alexidine dihydrochloride may be a novel therapeutic for sensitizing tumor cells to chemotherapy, this sensitization is probably functions largely independent of PTPMT1 expression in cells." (PMID 23326511, 2013).
PTPMT1 also shares sentences with these, for which no sentence is quoted: cardiomyopathy (1 paper); ischemic stroke (1); major depressive disorder (1); myopathy (1); myopia (1); neutropenia (1); Obesity (1); Progressive encephalopathy (1); senile cataract (1); Stroke (1); type II diabetes (1).